KLF4 (KLF transcription factor 4)
Diseases named in the same sentence as KLF4 in open-access papers (continued):
Sharing a sentence is not in itself a finding about the gene and the disease.
colon carcinoma (continued). "In contrast, one/three consensus Sp1 binding sites between −150/+1 bp of the Klf4 promoter have shown to be important for PDGF- or butyrate-induced Klf4 expression in VSMCs, colon cancer cells, or odontoblast." (PMID 33036290, 2020). "siRNA-depletion of Syndecan-1, and upregulation of heparanase increased the colon cancer stem cell phenotype based on sphere formation assays and phenotypic marker analysis (Side-population, NANOG, KLF4, NOTCH, Wnt, and TCF4 expression)." (PMID 32477959, 2020). "KLF4 directly represses BMI1 transcription, and thereby regulates BMI1, which is required for colon cancer proliferation." (PMID 27314328, 2016). "We transduced OCT3/4, SOX2, KLF4, or a mixture of the three (hereafter, OSK) into the SW480 human colon cancer cell line using retrovirus vectors, and also a Mock vector (empty vector) was used as a control." (PMID 25006808, 2014). "Using an in vitro setup, in the epithelial-like colon carcinoma cell line HCT-116, we demonstrated a 50% reduction of KLF4 mRNA abundance upon transfection with miR-10a." (PMID 24204315, 2013). "The expression levels of KLF4 in SW620, HT29, SW480, HCT116, DLD-1, and LOVO human colon cancer cell lines as well as FHC, a normal colon epithelial cell line, were analyzed using real-time PCR and Western blotting analysis." (PMID 23418515, 2013). "Therefore, KLF4 may be a potential target when we develop strategies to treat colon cancer." (PMID 23418515, 2013). "Interestingly, other transcription factors including KLF4, OCT4, and SOX2 were unaffected by c-Fos in colon cancer cells." (PMID 38233377, 2024). "KLF4 mediates the effects of mesalazine, also known as 5-aminosalicylic acid (5-ASA), an aminosalicylate anti-inflammatory drug, on the β-catenin pathway in colon cancer cells." (PMID 33266506, 2020). "Kruppel Like Factor 4 (KLF4) is a target of the tumor suppressor gene Adenomatous Polyposis Coli (APC) and its overexpression reduces cell migration and invasion in vitro and tumorigenicity of colon cancer cells in vivo." (PMID 31337362, 2019). "In colon cancer models some authors have reported that miR-103/107 may promote metastasis by targeting the metastasis suppressors DAPK and KLF4." (PMID 25197016, 2014). "Second, knocking down the KLF4 expression in DLD-S cells reduced the number of CD133+ cells and reduced the expression levels of colon cancer stem cell marker genes and those cells could not effectively form spheres in serum-free medium." (PMID 23418515, 2013). "Other known colon cancer miRNA signatures were confirmed, such as an increase in miR-21 and a decrease in miR-98, but no concordance was observed for these miRNAs and KLF4 (data not shown)." (PMID 23006636, 2012). "In an initial screen of human colon cancer cell lines, SW48 cells had the highest constitutive levels of miR-206 and low relative expression of KLF4, whereas SW480 cells exhibited the highest endogenous KLF4 levels and low miR-206 expression." (PMID 23006636, 2012). "Indeed, in colon cancer cells, KLF4 was recently identified as one of the downstream targets of IFNγ and STAT1, mediated through interaction of STAT1 with a GAS element present in the KLF4 promoter." (PMID 41155497, 2025). "Similarly, in human colon cancer, a set of TFs such as OCT3/4, SOX2 and KLF4 could transform colon cancer cells into CSCs." (PMID 29799161, 2018). "In addition, we could confirm the NRF2 increase in sphere-cultured colon carcinoma HCT116 and ovarian carcinoma A2780: levels of NRF2 protein along with CSC marker KLF4 were significantly higher in spheres when compared to corresponding monolayer cells." (PMID 25717032, 2015).
colon carcinoma (continued). "This notion was also supported in the late study using murine model, in which an aberrant expression of miR-103/107 could enhance the invasion and liver metastasis in colon cancer through a mechanism of inhibiting the expression of DAPK and KLF4, by which KLF4 can influence cell cycle arrest." (PMID 26064956, 2015). "Taken together, these results suggest that KLF4 is most likely expressed in CD133+ subpopulation and DLD-1-derived spheroid cells, which enriched CSCs, challenging the previous conclusion of that KLF4 functions as a tumor suppressor in colon cancer progression." (PMID 23418515, 2013). "To date, no study has confirmed whether KLF4 is an important regulator of colon cancer stem cell apoptosis and renewal, and whether it plays the vital role in colon CSCs." (PMID 23418515, 2013). "Information on tumor stage was available for some, but not all, of the human primary colon cancers examined here, and as a consequence we could not corroborate an early report suggesting KLF4 as a prognostic predictor of colon cancer." (PMID 23006636, 2012). "Our results uncovered that NANOG, rather than KLF4, OCT4, and SOX2, was significantly up-regulated in FOS-overexpressed colon cancer cells." (PMID 38233377, 2024). "KLF4 mRNA is consistently and strongly induced in our COX-2 but not in mPGES1 overexpressing colon carcinoma cells and it was shown that COX-2 and KLF4 colocalized in carcinoma cells of CRC tumor samples." (PMID 32410997, 2020).
lung carcinoma (83 papers, 2007 to 2026). "For example, poor outcome in non‐small cell lung cancer patients has been associated with high expression of KLF4 in the nucleus but low KLF4 expression in the cytoplasm." (PMID 40066228, 2025). "KLF4 with macrophage infiltration and polarization in lung cancer microenvironment was closely associated with macrophage M2 polarization promoting cancer cell growth and survival." (PMID 38560274, 2024). "The KM plot analysis showed that the overregulation of three oncogenes (SOX4, BZW2, and FOXM1) as well the downregulation of four tumor suppressors (SOX17, ZBTB16, TAL1, and KLF4) is associated with worse overall survival (OS) for lung cancer patients." (PMID 36661515, 2023). "KLF4 has been shown to be associated with the aggressiveness of many types of cancer and was also reported to be a tumor suppressor gene in lung cancer." (PMID 31969824, 2019). "To identify the mechanism by which KLF4 regulates lung cancer growth, we searched for potential targets of KLF4 that are implicated in tumor development and progression." (PMID 27153563, 2016). "Further improved understanding of the mechanism underlying KLF4-mediated inhibition will result in novel therapies for treating lung cancer." (PMID 27153563, 2016). "To investigate the biological activities of KLF4 in lung cancer cells, we first knocked down KLF4 expression in H1299 cells, which caused significantly increased cell proliferation compared with the control siRNA (siCtrl) treated cells." (PMID 27153563, 2016). "Survival analysis indicated that the combination of loss of KLF4 and the overexpression of hTERT were significantly correlated with poor prognosis in lung cancer patients." (PMID 27153563, 2016). "Klf4 was first identified as a tumor suppressor, owing to frequent loss of Klf4 expression in gastric, colon, esophageal, bladder and lung cancer, as well as in pancreatic ductal carcinoma." (PMID 23599755, 2013). "The significant loss of KLF4 has been reported in sporadic colonic adenomas and carcinomas, gastric cancers, bladder cell lines and tissue, and lung cancer." (PMID 17472751, 2007). "Furthermore, we investigated the association between ADRB2 and KLF4 in immune cell infiltration among lung cancer patients by leveraging the TIMER2.0 database." (PMID 40276761, 2025). "However, it is probably the result of loss of Klf4-induced repression of Tert, given previous studies showing that Klf4 downregulates hTERT expression and telomerase activity to inhibit lung carcinoma growth." (PMID 38258907, 2024). "Importantly, increased KLF4 expression was associated with a worse OS among lung cancer patients from an online database." (PMID 35982899, 2022). "Furthermore, higher KLF4 expression is associated with poorer overall survival (OS) in lung cancer patients, as well as reduced progression‐free survival (PFS) in patients undergoing anti‐PD1 (Immune‐checkpoint inhibitor) ICB therapy, underscoring its prognostic significance." (PMID 40755294, 2025). "KLF4 attenuates the invasiveness of lung cancer cells by transcriptionally downregulating NF‐κB2 and CXCR2, thereby attenuating prometastatic signaling pathways." (PMID 41532367, 2026). "Low expression of KLF4 (together with other core genes) is significantly correlated with the poor OS of lung cancer patients." (PMID 41463190, 2025). "KLF4 has been reported as a tumor suppressor in colon adenomas, gastrointestinal tumors, lung cancer." (PMID 40616161, 2025). "This stabilization was shown to increase the binding of AHR to the promoter regions of the stemness genes such as ABCG2, KLF4, and cMYC, promoting tumor growth and enhancing lung cancer stem-like properties." (PMID 40303305, 2025). "To investigate the function of KLF4 during carcinogenesis, we first examined the expression of KLF4 in lung cancer tissues." (PMID 38808570, 2024).
lung carcinoma (continued). "The low expression of KLF4 (together with other hub-genes) correlated significantly with the poor overall survival (OS) of lung cancer patients." (PMID 39135777, 2024). "Remarkably, we observed an increased expression of p21 both at the mRNA and protein levels in lung cancer cells after activation of the OSKM cassette or after individual expression of Oct4 or Klf4." (PMID 39587064, 2024). "In line with this, Oct4 has been shown to activate Caspase 3 and 8 during cell reprogramming, while Klf4 has been reported to regulate adult lung tumor-initiating cells and represses K-Ras-mediated lung cancer." (PMID 39587064, 2024). "It appeared that overexpression of KLF4 significantly suppressed the proliferation and migration of lung cancer cells." (PMID 38808570, 2024). "Analysis of cell growth at long periods of time showed that reducing the expression of p21 in the context of single overexpression of OCT4 or KLF4 resulted in the partial protection of the growth of lung cancer cells." (PMID 39587064, 2024). "KLF4 protein levels were significantly upregulated when MACC1 was knocked down in lung cancer cell lines H1299 and H2170." (PMID 39695175, 2024). "Taken together, these results indicated that KLF4 is a key effector for the MACC1 silence suppress stem-like properties in lung cancer." (PMID 39695175, 2024). "In agreement, knockdown of p21 expression using shRNA, alleviates the apoptosis and senescence induction and partially rescues the growth of full OSKM or individual Oct4 or Klf4 expressing lung cancer cells." (PMID 39587064, 2024). "Consistently, restoration of KLF4 expression alone was sufficient to shut off cell motility and eliminate the progenitor-like population of lung cancer cells." (PMID 39695175, 2024). "One study reported that over-expression of KLF4 in lung cancer cells inhibited cell migration and invasion." (PMID 38808570, 2024). "Similar results also obtained in colony formation and cell viability assay (cck-8), by knocking down KLF4 in the shMACC1 stable cell line, the proliferation ability and cell viability of lung cancer cells can be significantly restored." (PMID 39695175, 2024). "In lung cancer, most evidences suggested a tumour suppressive role of KLF4 in the cases of NSCLC and small cell lung cancer (SCLC)." (PMID 38924680, 2024). "Histone deacetylase (HDAC) inhibition seems to be the most relevant mechanism controlling KLF4 expression in lung cancer cell lines A549 and H460." (PMID 39135777, 2024). "Zhuan found that TRHDE-AS1 can overexpress to inhibit cell proliferation and invasion in lung cancer through the miRNA-103/KLF4 axis." (PMID 37239411, 2023). "For instance, KLF4 functions as an oncogene in B non‐Hodgkin lymphoma but appears as a tumour suppressor in several epithelial cancers, such as lung cancer and cancers in the digestive tract." (PMID 37400979, 2023). "The seven top deregulated transcription factors (SOX4, SOX17, BZW2, FOXM1, ZBTB16, TAL1, and KLF4) consistently appear to be co-expressed with other frequent DEGs and transcription factors throughout the analysis in lung cancer and PAH." (PMID 36661515, 2023). "A recent study reported that USP10 regulates KLF4 stability and exerts a tumor-suppressive role in lung cancer." (PMID 35277183, 2022). "GKLF, also named KLF4, in lung cancer tissues was found to regulate lung tumor-initiating cells at a considerably lower level than that in normal lung tissues." (PMID 35677637, 2022). "Some studies have shown that KLF4 expression is decreased in gastric cancers, hepatocellular carcinoma and lung cancer and is a favourable prognostic factor." (PMID 35177016, 2022). "Previous reports showed that KLF4, a zinc finger-type transcription factor, played a pivotal and different role in the development of various cancers, including lung cancer, HCC, and pancreatic cancer." (PMID 35637651, 2022).
lung carcinoma (continued). "KLF3 and KLF4 inhibit the proliferation, migration, and invasion of lung cancer cells, and induce cell cycle arrest and apoptosis." (PMID 35387557, 2022). "The mechanisms underlying the variable KLF4 expression levels in NSCLC and how KLF4 functions in the development and progression of lung cancer, including NSCLCs, are worthy of future investigations." (PMID 35982899, 2022). "The overexpression of the noncoding long RNA TRHDE-AS1 inhibits lung cancer progression via the miRNA-103/KLF4 axis." (PMID 35910194, 2022). "We examined the expression pattern of KLF4 in multiple tissues and found that the highest level of KLF4 in lung, which was supported by KLF4, inhibits lung carcinoma growth through downregulating hTERT expression and telomerase activity in mice." (PMID 34421986, 2021). "Subsequently, we validated that METTL3/YTHDF2 m6A axis also repressed KLF4 expression in lung cancer." (PMID 34774019, 2021). "Overexpression of the long noncoding RNA TRHDE-AS1 was shown to inhibit the progression of lung cancer via the miRNA-103/KLF4 axis." (PMID 34178671, 2021). "Consistently, KLF4 has been shown to prevent EMT in human corneal epithelia as well as in some types of lung cancers." (PMID 32937756, 2020). "In the current study, both the clinical implications and biological effects of PLAC8 in lung cancer (LC) progression were investigated, and we identified and described the novel Krüppel-like factor 4 (KLF4)/PLAC8 regulatory pathway in cancer progression." (PMID 29789534, 2018). "Increased TRPM7 expression was associated with enhanced SOX2, KLF4, and CD133, Hsp90α, uPA, and MMP2 expression in lung cancer cells." (PMID 30477473, 2018). "Dysregulation of KLF4 has been observed in a number of human cancers, including gastrointestinal, pancreas, bladder, and lung cancer." (PMID 30176890, 2018). "Overexpression of KLF4 inhibits invasiveness of lung cancer cells (A549 and H322) by suppressing SPARC expression." (PMID 28969021, 2017). "In this study, we established technologies to generate lung CSC-like cells from human lung cancer cell line A549 by introducing OCT3/4, SOX2 and KLF4, and to construct “lung cancer organoids” in vitro that mimicked human lung cancer tissues." (PMID 28951614, 2017). "Next, we systematically assayed the KLF4 and hTERT protein levels using immunohistochemical staining of tissue microarrays, including lung cancer tissues and their comparable normal counterparts." (PMID 27153563, 2016). "Our previous studies have shown that the expression of KLF4 is dramatically reduced in primary lung cancer tissue and that it functions as a tumor suppressor in primary lung cancer." (PMID 27153563, 2016). "Restoration of KLF4 expression in lung cancer cells inhibited cell growth in vitro and tumor formation in vivo." (PMID 27153563, 2016). "In this study, we found that KLF4 negatively regulated hTERT expression and telomerase activity in lung cancer cell lines and a mouse model." (PMID 27153563, 2016). "In this study, we aimed to examine the role of KLF4 and its putative target, hTERT, in lung cancer development and progression, which was followed by elucidating the underlying molecular mechanisms and clinical significance." (PMID 27153563, 2016). "KLF4 itself has been identified as a tumor suppressor in some tumor types, such as lung cancer, gastric cancer, colorectal cancers, urothelial cancer and cervical cancer." (PMID 27153563, 2016). "Previously, we have reported on the tumor suppressive function of KLF4 in lung cancer; however, its precise regulatory mechanism remains elusive." (PMID 27153563, 2016). "In this study, using the combination of a lung tumor tissue microarray, cell lines and animal models, we investigated the interaction between KLF4 and hTERT in lung cancer." (PMID 27153563, 2016). "Principal molecular markers of the MAPK signaling pathway were tested in lung cancer cells that have altered KLF4 levels." (PMID 27153563, 2016).